S100A8 (S100 calcium binding protein A8)
Diseases named in the same sentence as S100A8 in open-access papers (continued):
Sharing a sentence is not in itself a finding about the gene and the disease.
Hepatic fibrosis (6 papers, 2010 to 2025). The presence of excessive fibrous connective tissue in the liver. "Single-cell transcriptomic studies have linked S100A8+ macrophages to liver fibrosis, and S100A8-mediated pyroptotic macrophage death has been shown to activate hepatic stellate cells and promote liver fibrosis." (PMID 41178716, 2025). "In this study, since S100A8-induced NLRP3 inflammasome-dependent pyroptosis is correlated with liver fibrosis, its diagnostic value for the onset and progression of liver fibrosis was analyzed." (PMID 36429008, 2022). "IHC and enzyme-linked immunosorbent assay (ELISA) results showed that S100A8 and S100A9 were both significantly elevated in liver fibrosis patients compared to HCs." (PMID 36429008, 2022). "Staining signals of the pyroptosis mediator NLRP3 alone with S100A8 were gradually increased with the aggravation of liver fibrosis in mouse models from 4 to 8 weeks." (PMID 36429008, 2022). "Specifically, S100A8 increased more dramatically than S100A9 during the progression of liver fibrosis, implying an important role of S100A8 in the pathogenesis of liver fibrosis." (PMID 36429008, 2022). "Notably, S100A8 increased more dramatically than S100A9 during the progression of liver fibrosis from fibrosis F0 to F4." (PMID 36429008, 2022). "However, the detailed molecular mechanism controlling the transcription of S100A8/A9 genes during liver fibrosis process is necessary for further extended analysis in future studies." (PMID 36429008, 2022). "Here, we further explored whether S100A8 can promote liver fibrosis by inducing NLRP3 inflammasome-dependent pyroptotic death in macrophages." (PMID 36429008, 2022). "In addition, elevated S100A8 in liver fibrosis patients was correlated with pyroptosis-related indicators." (PMID 36429008, 2022). "Furthermore, striking up-regulation of neutrophil markers and the localisation of neutrophils and the neutrophil chemokine S100A8 to fibrotic areas suggest the involvement of neutrophils in S. japonicum-induced hepatic fibrosis." (PMID 20161726, 2010). "Therefore, we wondered whether CD36 mediates S100A8-induced ROS production and NF-κB pathway activation in liver fibrosis progression, which requires further studies to investigate." (PMID 36429008, 2022). "In conclusion, S100A8-mediated NLRP3 inflammasome-dependent pyroptosis by TLR4/NF-κB activation and ROS production in macrophages facilitates liver fibrosis progression." (PMID 36429008, 2022). "As two members of DAMPs, S100A8 and S100A9, can serve as triggering factors and amplifiers of inflammation, and we have previously found that S100A9 increases in liver fibrosis." (PMID 36429008, 2022). "Based on the role of S100A8-elicited NLRP3 pyroptosis in liver fibrosis, we chose a well-defined cohort of liver fibrosis patients to assess the clinical importance of circulating S100A8, GSDMD, IL-1β, and IL-18 for predicting the occurrence and progression of disease." (PMID 36429008, 2022). "In conclusion, the current study suggests that S100A8 stimulates NLRP3 inflammasome-dependent pyroptosis in macrophages via activating TLR4/NF-κB signaling and inducing ROS abundance, which finally facilitates the progression of liver fibrosis." (PMID 36429008, 2022). "Furthermore, serum S100A8 and pyroptosis-related indicators GSDMD, IL-1β, and IL-18 levels were all gradually augmented during the progression of the liver fibrosis model." (PMID 36429008, 2022). "Similarly, elevated levels of S100A8 and S100A9 were verified in clinical samples and CCl4-induced mouse model studies, and their levels were strongly related to the severity of liver fibrosis." (PMID 36429008, 2022). "In the present study, we demonstrated that S100A8 as a crucial DAMP could stimulate NLRP3 inflammasome-dependent pyroptotic macrophage death by activating TLR4-dependent NF-κB and inducing ROS abundance, finally facilitating liver fibrosis progression." (PMID 36429008, 2022).
Hepatic fibrosis (continued). "Given this, we hypothesized that S100A8 and/or S100A9 may regulate NLRP3 inflammasome-dependent pyroptosis to establish a proinflammatory microenvironment, thereby potentiating the progression of liver fibrosis." (PMID 36429008, 2022).
idiopathic pulmonary fibrosis (6 papers, 2015 to 2025). Idiopathic pulmonary fibrosis (IPF) is a nonneoplastic pulmonary disease that is characterized by the formation of scar tissue within the lungs in the absence of any known cause. "S100A8 and S100A9 are upregulated in the acute exacerbations of idiopathic pulmonary fibrosis (IPF) suggesting roles of different signaling pathways like Clathrin-mediated endocytosis signaling, atherosclerosis signaling, and IL2 signaling in the pathogenesis of acute exacerbations of IPF." (PMID 34239729, 2021).
ischemia (6 papers, 2013 to 2025). A hypoperfusion of the BLOOD through an organ or tissue caused by a PATHOLOGIC CONSTRICTION or obstruction of its BLOOD VESSELS, or an absence of BLOOD CIRCULATION. "Following ischemia, S100A8/A9 is released in circulation, mainly from activated neutrophils and monocytes/macrophages." (PMID 41155408, 2025). "During ischemia/ischemia-reperfusion injury, S100A8/A9 promoted cardiac inflammatory response by stimulating leukocyte activation/infiltration, amplifying NF-κB signaling activation, and proinflammatory cytokine secretion." (PMID 38538601, 2024). "Collectively, S100A8/A9 is an important driver of various pathological processes during ischemia/ischemia-reperfusion injury." (PMID 38538601, 2024). "Treatment of mice with ischemia or angiotensin II also markedly increases the recruitment of neutrophils to the heart, thereby producing large amounts of S100A8/A9." (PMID 36768433, 2023). "In 6- and 24-h post-ischemia of a mouse model of permanent middle cerebral artery occlusion, S100A8 mRNA was only expressed in the ischemic region." (PMID 33530496, 2021). "Therefore, S100A8 may be involved in the inflammatory communication between microglia and neuron during ischemia." (PMID 33530496, 2021). "Moreover, genetic deletion or pharmacological inhibition of S100A8/A9 can inhibit the TLR4/NLRP3/IL-1β pathway, suppressing ischemia-induced granulopoiesis and improving cardiac dysfunction." (PMID 36768433, 2023). "As cardiac myocytes subjected to ischemia do not upregulate S100A8 and S100A9 mRNA and protein levels, S100A8/A9 is probably released from activated monocytes and neutrophils recruited to the site of the injury." (PMID 24453429, 2013).
lupus nephritis (6 papers, 2020 to 2025). Glomerulonephritis in the context of systemic lupus erythematosus. "SLE can increase the levels of S100A8, S100A9, and S100A12 in serum and the combination of the three proteins can be used as biomarkers for lupus nephritis caused by SLE." (PMID 35796625, 2022). "The S100A8/A9 heterodimer, the dominant form in serum, has been observed in patients with SLE as well as in those with cardiovascular disease in SLE and active lupus nephritis and can predict responses to treatment of SLE." (PMID 35529863, 2022). "As expected, our data indicate a significant increase in urine S100A8 levels in lupus nephritis compared with extrarenal SLE, and intriguingly, S100A8 in serum and saliva also showed a significant increase in patients with lupus nephritis." (PMID 35529863, 2022).
lymph node metastasis (6 papers, 2012 to 2023). "Copy number data for cases with lymph node metastases was available for 94 cases and 24/94 (25%) showed S100A8 CN ≥ 4 in the primary tumor." (PMID 37450087, 2023). "We found that S100A8 and S100A9 were elevated in CRC, and their expression in tumor cells was associated with the differentiation, Dukes stage and lymph node metastasis." (PMID 23637971, 2013). "S100A8 and S100A9 were elevated in more than 50% of CRC tissues and their expression in tumor cells was associated with differentiation, Dukes stage and lymph node metastasis." (PMID 23637971, 2013). "In the present study, we confirmed the elevation of S100A8 and S100A9 in CRC and found that their elevation in tumor cells was not only associated with histological differentiation but also with Dukes stage and lymph node metastasis in CRC." (PMID 23637971, 2013). "Of these, 10/24 (42%) also had increased S100A8 CN in the lymph-node metastasis while 14/24 (58%) did not (p = 0.005)." (PMID 37450087, 2023). "We used COX analysis to evaluate the effects of multiple variables, including age, tumor location, histological type, tumor grade, tumor stage, tumor size, lymph node metastasis, ER status, PR status, HER2 status, menopause status and S100A8 expression level, on OS and DFS." (PMID 30456203, 2018).
malaria (6 papers, 2013 to 2024). Malaria is a serious and sometimes fatal disease caused by a parasite that commonly infects a certain type of mosquito which feeds on humans. "The Ca + 2 and Zn + 2 binding heterodimeric protein S100A8/9 was a common protein family upregulated during active infections in bacteria and malaria, with the greatest decline during convalescence." (PMID 37831367, 2024). "In malaria, elevated serum or plasma levels of S100A8/A9 have been reported in two different studies." (PMID 27917875, 2016). "It means that some components of malaria parasites may directly affect DC maturation or induce the expression of S100A8 in iDC, which is used in DC maturation as self-feeding manner to be matured DC." (PMID 26438270, 2015). "The source of S100A8 in malaria remains unclear, although it is known to be secreted from monocytes, macrophages and neutrophils." (PMID 26438270, 2015). "Treg cells suppress the activity of cytotoxic T cells, which kill malaria parasites; therefore, the up-regulation of S100A8 in malaria patients may contribute to pathogen immune escape or tolerance." (PMID 26438270, 2015). "Therefore, the concentrations of S100A8 in 40 malaria patients who were confirmed to be infected with Korean isolates of P. vivax was first measured and compared with those of 40 healthy controls." (PMID 26438270, 2015). "Within innate myeloid cells, malaria drove changes to monocytes consistent with the induction of immunosuppressive MS1-like monocytes, which have high expression of alarmins S100A8/A9, along with RETN and ALOX5AP and reduced expression of MHC class II." (PMID 37968278, 2023). "The results show that in early malaria, selected immune response-related genes were up-regulated including α β and γ interferon-related genes, as well as genes of IL-15, CD36, chemokines (CXCL10, CCL2, S100A8/9, CXCL9, and CXCL11), TRAIL and IgG Fc receptors." (PMID 24188121, 2013). "Interestingly, the level of S100A8 did not coincide with that of anti-malaria antibodies (P = 0.8806)." (PMID 26438270, 2015).
multiple myeloma (6 papers, 2022 to 2025). "To investigate the involvement of S100A8/S100A9 in multiple myeloma progression, we evaluated the amount of these proteins in the BM of tumor-free and DP42 myeloma-bearing mice." (PMID 36923707, 2023). "Our study demonstrated a significant role of the myeloid-derived proteins S100A8/S100A9 in the progression of multiple myeloma." (PMID 36923707, 2023). "Our work provided first evidence that S100A8/S100A9 proteins are at least partially responsible for the supporting megakaryopoiesis in the myeloma BM." (PMID 36923707, 2023). "To determine a possible biological role of S100A8/S100A9 in multiple myeloma, we assessed the therapeutic effect of TQ in different models of multiple myeloma." (PMID 36923707, 2023). "An increased number of BM CD11b+Gr1+ cells (MDSC) as well as increased production of S100A8/S100A9 by these cells contributed to the elevated levels of S100A8/S100A9 proteins in multiple myeloma–bearing hosts." (PMID 36923707, 2023). "Our results demonstrated a novel mechanism by which S100A8/S100A9 can regulate BM TME in multiple myeloma via upregulation of MKs." (PMID 36923707, 2023). "The levels of S100A8/S100A9 in the BM of patient with multiple myeloma were significantly elevated when compared with those in peripheral blood of these patients as well as to the S100A8/S100A9 levels reported in healthy donors." (PMID 36923707, 2023). "As a result, the increased amount of S100A8/S100A9 in multiple myeloma BM was not sufficient to cause a detectable effect on myeloid cells." (PMID 36923707, 2023). "We assessed the role of S100A8/S100A9 proteins in BM angiogenesis in the model of multiple myeloma." (PMID 36923707, 2023). "Next, we evaluated the presence of S100A8/S100A9 protein in patients with multiple myeloma." (PMID 36923707, 2023). "Thus, the higher level of S100A8/S100A9 in the BM of multiple myeloma–bearing mice was associated the accumulation of MDSC in the presence of tumor cells and increased production of S100A8/S100A9 by these MDSC." (PMID 36923707, 2023). "We hypothesized that S100A8/S100A9 may have a particularly important role in multiple myeloma growth given the abundance of MDSC in the myeloma BM TME and that TQ would therefore be effective at inhibiting multiple myeloma progression." (PMID 36923707, 2023). "However, more studies are needed to better understand a clinical significance of S100A8/S100A9 within the established multiple myeloma—myeloid–MK axis that may regulate megakaryopoiesis in patients with multiple myeloma." (PMID 36923707, 2023). "Specifically, we discovered a novel role of S100A8/S100A9, the most abundant proteins produced by neutrophils and monocytes, in regulation of myeloma progression via promotion of the megakaryocyte expansion and angiogenesis." (PMID 36923707, 2023). "Here, we describe a novel mechanism by which S100A8/S100A9 proteins produced by BM neutrophils and monocytes promote the expansion of megakaryocytes supporting multiple myeloma progression." (PMID 36923707, 2023). "As a potent inhibitor of S100a8/a9, ABR‐238901 treatment has been shown to reduce tumor load in combination with Bortezomib in experimental multiple myeloma." (PMID 38023700, 2023). "Interestingly, S100 genes have been found to confer resistance to proteasome inhibitors, of which the members S100A8 and A9 were among the genes with the greatest increase in expression in relapse versus diagnosis LCE-multiple myeloma." (PMID 39699274, 2025).
myeloid leukemia (6 papers, 2012 to 2025). A clonal proliferation of myeloid cells and their precursors in the bone marrow, peripheral blood, and spleen. "One transgenic strategy (using the S100A8 (MRP8) 5′ flanking region) resulted in myeloid leukemia, while two others (using Fes and Itgam (CD11b) promoters) did not." (PMID 23056333, 2012).
neuroblastoma (6 papers, 2012 to 2024). Neuroblastoma (NB) is the most common solid, extracranial childhood tumor. "Treatments with high 27-OH levels did not induce significant changes on the total levels of NFk-B in a similar way as S100A8 did; nevertheless, NFk-B nuclear translocation was observed in the human neuroblastoma cell line SH-SY5Y." (PMID 34449045, 2021). "This analysis revealed that 1.918 of the 18.469 differentially expressed neuroblastoma transcripts were neutrophil-related, which included highly specific neutrophil markers such as FCGR3B, FPR1, S100A8/9, and SIGLEC9, among others." (PMID 34503071, 2021).
pancreatitis (6 papers, 2021 to 2026). Inflammation of the pancreas. "Furthermore, in view of the intracellular and extracellular activities of S100A8/A9 in pancreatitis, it will be important to determine whether and how S100A8/A9 is involved in pancreatitis-initiated PDAC." (PMID 34527585, 2021). "Patients with PC-induced cachexia at diagnosis had significantly higher serum levels of S100A8, S100A9 and S100A8/A9 compared with PC patients without cachexia, patients with pancreatitis, and healthy controls." (PMID 37280516, 2023).
sarcoidosis (6 papers, 2006 to 2025). Sarcoidosis is a multisystemic disorder of unknown cause characterized by the formation of immune granulomas in involved organs. "Genomic, transcriptomic, and proteomic studies found that S100A8 is a gene with high potential for association with sarcoidosis being involved in regulating immune response, cellular proliferation, apoptosis, inhibition of protease activity, and lipid metabolism." (PMID 33567747, 2021). "A sarcoidosis-related inflammation is caused by the expression of interferon-γ (IFN-γ), interleukin-6, interleukin-23, and S100A8/A9, in turn leading to the immunosuppressive activity of MDSC." (PMID 35103216, 2022). "Similar to NL and NXG, sarcoidosis lesional macrophages upregulated expression of the macrophage polarization marker genes MARCO, FCGR3A, NR1H3; the ECM-encoding gene FN1; the protease-encoding gene CTSS; and genes associated with inflammation, S100A8 and CHI3L1." (PMID 39989459, 2025). "We might surmise that the inflammation associated with sarcoidosis, which is characterized by the expression of IFN, IL6, IL23, and S100A8/A9, shares a milieu with malignancies, which are distinguished by an elevated accumulation and immunosuppressive role of myeloid-derived suppressor cells (MDSC)." (PMID 37868478, 2023). "S100A8 and S100A9, myeloid-related proteins that act as growth factors, were found to be elevated in patients diagnosed with sarcoidosis along with an enhanced cytoplasmic expression in monocytes multinucleated giant cells in granulomas." (PMID 35103216, 2022). "It is intriguing to note that there is a positive correlation between S100A8/A9 expression and TNF-α release in alveolar macrophages from patients with active sarcoidosis." (PMID 16613612, 2006).
systemic sclerosis (6 papers, 2019 to 2025). A chronic disorder, possibly autoimmune, marked by excessive production of collagen which results in hardening and thickening of body tissues. "In a very initial paper, plasma levels of S100A8/A9 were found at elevated levels in the sera of some patients with connective tissue diseases, including systemic sclerosis." (PMID 32679721, 2020). "Infact, among S100 A proteins, S100A7, S100A8, S100A9, S100A12 have been already described as differentially expressed in other systemic autoimmune diseases and particularly in Systemic Sclerosis." (PMID 31249499, 2019).